AURKA (aurora kinase A)
Description:
Mitotic serine/threonine kinase that contributes to the regulation of cell cycle progression. Associates with the centrosome and the spindle microtubules during mitosis and plays a critical role in various mitotic events including the establishment of mitotic spindle, centrosome duplication, centrosome separation as well as maturation, chromosomal alignment, spindle assembly checkpoint, and cytokinesis. Required for normal spindle positioning during mitosis and for the localization of NUMA1 and DCTN1 to the cell cortex during metaphase. Required for initial activation of CDK1 at centrosomes. Phosphorylates MCRS1 which is required for MCRS1-mediated kinetochore fiber assembly and mitotic progression. Regulates KIF2A tubulin depolymerase activity. Important for microtubule formation and/or stabilization. Required for normal axon formation. Plays a role in microtubule remodeling during neurite extension. Phosphorylates its own inhibitors, the protein phosphatase type 1 (PP1) isoforms, to inhibit their activity. Inhibits cilia outgrowth (By similarity). Required for cilia disassembly via phosphorylation of HDAC6 and subsequent deacetylation of alpha-tubulin. Regulates protein levels of the anti-apoptosis protein BIRC5 by suppressing the expression of the SCF(FBXL7) E3 ubiquitin-protein ligase substrate adapter FBXL7 through the phosphorylation of the transcription factor FOXP1.
Synonyms: AIK; ARK1; AURA; BTAK; STK15; STK6; STK7; PPP1R47
Tractability: Small molecule: a drug acting on it is in phase 2 or 3 trials; a structure with a bound ligand is known; a high-quality ligand is known; it has a high-quality binding pocket; it belongs to a druggable protein family. Antibody: UniProt places it where antibodies can reach, with medium confidence; its Gene Ontology location is reachable by antibodies, with medium confidence. PROTAC: it is named in the literature on targeted protein degradation; UniProt records ubiquitination sites on it; ubiquitination databases record sites on it; a small molecule that binds it is known.
Target class: Other protein kinase AUR family; Other protein kinase group; Enzyme; Kinase; Protein Kinase
Chemical probes: ALISERTIB, AMG-900 (high quality), Aurora A inhibitor I, Aurora-compound 1 (high quality), DANUSERTIB, FMF-01-086-2 (high quality), FMF-03-145-1 (high quality), FMF-04-159-2 (high quality), JB170 (high quality), MK-5108 (high quality), PD070361, PD080716, PD080740, PD080955, PD081037, PD081099, PD081173, PD081213, PD081368, PD081512, and 51 more
Safety:
Unwanted effects reported when the protein is acted on. In parentheses: how it was acted on, where the effect was seen, and who reports it.
Mutagenic effect (inhibition; genetic toxicity; source: Brennan et al. (2024))
neutropenia (inhibition; blood; source: Brennan et al. (2024))
heart disease (cardiovascular system; source: Force et al. (2011))
Gene: Protein-coding gene on chromosome 20 (56,369,382 to 56,392,566, reverse strand). Ensembl gene ENSG00000087586.
Subcellular location: Cytoplasm, cytoskeleton, microtubule organizing center, centrosome; Cytoplasm, cytoskeleton, spindle pole; Cytoplasm, cytoskeleton, microtubule organizing center, centrosome, centriole; Cell projection, neuron projection; Cell projection, cilium; Cytoplasm, cytoskeleton, cilium basal body; Basolateral cell membrane
Subcellular location (Human Protein Atlas): Basal body; Centrosome; Mitotic spindle; Cytosol; Nucleoplasm
Pathways (Reactome):
Cell Cycle: APC/C:Cdh1 mediated degradation of Cdc20 and other APC/C:Cdh1 targeted proteins in late mitosis/early G1; AURKA Activation by TPX2; FBXL7 down-regulates AURKA during mitotic entry and in early mitosis; Interaction between PHLDA1 and AURKA; Regulation of PLK1 Activity at G2/M Transition
Metabolism of proteins: SUMOylation of DNA replication proteins
Gene Ontology:
Molecular function: molecular function activator activity; protein binding; protein heterodimerization activity; protein kinase activity; protein kinase binding; protein serine kinase activity; protein serine/threonine kinase activity; protein serine/threonine/tyrosine kinase activity; ATP binding
Biological process: cilium disassembly; liver regeneration; negative regulation of gene expression; negative regulation of protein binding; peptidyl-serine phosphorylation; positive regulation of mitochondrial fission; protein phosphorylation; regulation of protein stability; response to wounding; spindle organization; G2/M transition of mitotic cell cycle; mitotic cell cycle; mitotic spindle organization; positive regulation of mitotic cell cycle; positive regulation of mitotic nuclear division; protein autophosphorylation; regulation of centrosome cycle; regulation of cytokinesis; regulation of G2/M transition of mitotic cell cycle; cell cycle G2/M phase transition; centrosome cycle; meiotic cell cycle; meiotic spindle organization; microtubule cytoskeleton organization; and 3 more
Cellular component: centrosome; ciliary basal body; microtubule cytoskeleton; mitotic spindle pole; nucleus; perinuclear region of cytoplasm; spindle microtubule; spindle pole centrosome; basolateral plasma membrane; chromosome passenger complex; cytosol; kinetochore; midbody; nucleoplasm; spindle; spindle midzone; spindle pole; centriole; cilium; neuron projection
Genetic constraint (gnomAD): Loss-of-function variants: 16 observed, 45.99 expected, observed/expected ratio (o/e) 0.35, 90% interval 0.23 to 0.53. The upper end of that interval is the gene's LOEUF score, 0.53, which puts it in group 2 of 6, group 1 being the genes least tolerant of losing a copy. Missense variants: 304 observed, 469.1 expected, observed/expected ratio (o/e) 0.65, 90% interval 0.59 to 0.71. Synonymous variants: 164 observed, 166.7 expected, observed/expected ratio (o/e) 0.98, 90% interval 0.87 to 1.12.
Homologues: Orthologues: chimpanzee AURKA (99% identical), macaque AURKA (98% identical), dog AURKA (90% identical), rabbit AURKA (87% identical), rat Aurka (84% identical), mouse Aurka (82% identical), tropical clawed frog aurka (65% identical), zebrafish aurka (56% identical), Drosophila melanogaster aurA (47% identical). Paralogues in human: AURKB (52% identical), AURKC (49% identical).
Diseases named in the same sentence as AURKA in open-access papers:
AURKA is named in the same sentence as 262 diseases in open-access papers, as found by Europe PMC text mining. Sharing a sentence is not in itself a finding about the gene and the disease. The quoted sentences say what the papers report.
breast cancer (250 papers, 2001 to 2026). A primary or metastatic malignant neoplasm involving the breast. "In Rb1-deficient tumors—including CDK4/6i-resistant breast cancer—upregulation of mitosis-associated E2F target genes provides a therapeutic opportunity for AURKA inhibitors to trigger replication stress via synthetic lethality, leading to tumor cell death." (PMID 40949156, 2025). "High levels of AURKA expression in approximately 73% of breast cancer patients are associated with decreased survival rates and resistance to many anticancer drugs." (PMID 41007338, 2025). "In cancer, abnormal expression or mutations of the AURKA gene are closely associated with the occurrence and development of various cancers, including breast cancer, ovarian cancer, gastric cancer, and others." (PMID 38673957, 2024). "Our findings point to AURKA as a marker for increased DNA damage and DNA repair deficiency and suggest AURKA as a biomarker of clinical relevance in young breast cancer." (PMID 39198859, 2024). "Our findings indicate higher AURKA expression in young breast cancer, and associations between high Aurora-A/AURKA and aggressive tumor features, including higher tumor cell proliferation, and shorter survival, in the young." (PMID 39198859, 2024). "A recent study suggests that AURKA-HMMR, a genetic variant of AURKA, is linked to increased breast cancer risk in BRCA1 and BRCA2 mutation carriers." (PMID 38886738, 2024). "High AURKA mRNA expression was significantly associated with decreased relapse-free survival and post progression survival in breast cancer patients." (PMID 37415951, 2023). "Taken together, the discoveries of the present study not only highlight an innovative performance of oncogenic AURKA in controlling pan-breast cancer-associated RNA splicing, but also provide bases for the design of new strategies for breast cancer treatment." (PMID 37415951, 2023). "Subclonal diversity and dynamics were evident across all cases with potential therapy resistant subclones detected containing known HER2+ breast cancer driver genes such as AURKA or novel candidate mutations such as RNF43 for future studies." (PMID 37758711, 2023). "AURKA is known to regulate cell-cycle progression, and its overexpression in breast cancer is commonly associated with an ER-low/basal phenotype." (PMID 37760421, 2023). "One is that AURKA expression is highly associated with spliceosome activity by Pearson correlation analysis of whole-genome gene expression profile (clinical breast cancer samples from TCGA and METABRIC) with spliceosome activity score." (PMID 35361747, 2022). "AURKA plays an important role in cell cycle progression by promoting cell entry into mitosis, and is associated with increased risk of developing breast cancer." (PMID 34675265, 2021). "This meta-analysis indicated that the AURKA rs2273535 T>A polymorphism was associated with an overall increased cancer risk, especially breast cancer." (PMID 32733797, 2020). "For specific malignancy development associated with AURKA polymorphism, AURKA SNP rs6024836 was correlated with a higher susceptibility to breast cancer after multivariable analysis." (PMID 33050100, 2020). "The AurkA polymorphism has also been reported for other malignancies as well e.g., breast cancer and hepatocellular carcinomas." (PMID 29560108, 2018). "A meta-analysis suggested that AURKA rs1047972 is associated with a decreased breast cancer risk in Caucasians, while AURKA rs2273535 polymorphism is associated with an increased risk of breast cancer." (PMID 29678897, 2018). "In estrogen receptor-positive (ER+) breast cancer models, activation of Aurora A kinase (AURKA) is associated with downregulation of ERα expression and resistance to endocrine therapy." (PMID 29289986, 2018). "In breast cancer, the overexpression of AURKA is also linked to poor survival and it is associated with the overexpression of the human growth factor receptor 2 (HER2) and progesterone receptor." (PMID 30070631, 2018).
breast cancer (continued). "A study found that the AURKA rs2273535 polymorphism increases the risk of breast cancer, and that the rs1047972 polymorphism is a protective factor for breast cancer." (PMID 28152093, 2017). "Previous studies have also suggested that the AURKA rs2273535 polymorphism is associated with a high risk of breast cancer, particularly in Asians." (PMID 28152093, 2017). "A high expression of Aurora Kinase A (AURKA), a key regulator of chromosome segregation and cytokinesis, has been extensively associated with aggressiveness of ER+ breast cancer tumours and patients survival." (PMID 27341628, 2016). "Here we show that AURKA translocates to the nucleus and causes distinct oncogenic properties in malignant cells by enhancing breast cancer stem cell (BCSC) phenotype." (PMID 26782714, 2016). "Variation in CSTF1, located next to AURKA, was also found to be associated with breast cancer risk in BRCA2 mutation carriers: rs2426618 per-allele HR = 1.10, 95% CI 1.03 – 1.16, p = 0.005 (FDR-adjusted p = 0.045)." (PMID 25830658, 2015). "Published data on the association between AURKA polymorphisms and breast cancer (BC) risk are inconclusive." (PMID 25253995, 2014). "The loss of 5qter, a genomic region surrounding HMMR/RHAMM, is a frequent event in basal subtype breast cancer, and this genomic loss associates with an increase in the expression of AURKA in trans." (PMID 23328114, 2013). "We find that amplification of the MYC locus and the loss of the RB/INTS6 locus is evolutionarily conserved in mouse and human mammary tumor development, and that AURKA amplification is conserved in mouse and human BRCA2-mutated tumors." (PMID 20735817, 2010). "AURKA amplification has also been implicated in resistance to CDK4/6i in ER+/HER2− breast cancer." (PMID 40949156, 2025). "Interestingly, transcript AURKA-203 contains exon III that is thought to be implicated in breast cancer, which is also the type of cancer showing the second highest change in AURKA SLR as recorded by the APAtrap analysis." (PMID 39527514, 2024). "AURKA is commonly overexpressed in breast cancers with BRCA2 mutations." (PMID 39334449, 2024). "AURKA activity is associated with drug resistance in breast cancer." (PMID 36902486, 2023). "In addition, the association of aurora kinase A with drug resistance has been reported in several cancers, including gastric cancer, prostate cancer, and breast cancer." (PMID 35745617, 2022). "In addition, a high expression level of SMARCA4 or AURKA was associated with poor survival or metastasis-free survival in breast cancer patients." (PMID 34272397, 2021). "Some SNP polymorphisms could increase the risk of cancer in individuals such as the AURKA rs2273535 polymorphism in breast cancer." (PMID 34337875, 2021). "Abnormal amplification or overexpression of AURKA could be associated with high occurrence of cancers including gastric cancer, ovarian cancer, breast cancer, etc." (PMID 31706255, 2019). "Furthermore, there were related studies reported that Caucasians carrying AURKA rs1047972 T>C had a relatively low risk of developing breast cancer." (PMID 31636670, 2019). "Interestingly, high nuclear AURKA expression favors breast cancer stemness and is associated with poor patient prognosis." (PMID 30250494, 2018). "However, the AURKA rs1047972 polymorphism has been shown to reduce the incidence of breast cancer in Caucasians." (PMID 28152093, 2017). "Therefore, AURKA has been regarded as a prognostic marker of breast cancer arising from BRCA2 mutation." (PMID 28147341, 2017). "Previous study demonstrated that AURKA is commonly overexpressed in breast cancers with BRCA2 mutation and overexpressed AURKA could also suppress BRCA2 in ovarian cancer, indicating that there exists a negative correlation between AURKA and BRCA2." (PMID 28147341, 2017).
breast cancer (continued). "In addition to its well-defined role in mitosis, the overexpression of AURKA and upregulation of its enzymatic activity have been linked to tumorigenesis, specifically in ovarian, prostate, esophageal, gastric, colon and breast cancers." (PMID 27121204, 2016). "AurkA overexpression was previously found in breast cancer and associated to its ability in controlling chromosome segregation during mitosis, however whether it may affect breast cancer cells, endorsed with stem properties (BCICs), is still unclear." (PMID 27341528, 2016). "Further, B-MYB and FOXM1 target genes, such as CCNB1 and AURKA, are associated with breast cancer." (PMID 25909288, 2015). "Through a chemical genetic screen and a suite of drug mechanism-of-action studies, we here identify SYK-dependent STAT3 activation as a novel critical vulnerability of basal-like breast cancer cells, next to AURKA, which was previously implicated to be a potential target in BLBC." (PMID 25699542, 2015). "While the HMMR association study in BRCA1/2 mutation carriers drew on a partial dataset from the Consortium of Investigators of Modifiers of BRCA1/2 (CIMBA), the depicted mechanistic model highlighted additional gene candidates for breast cancer risk; i.e., AURKA, TPX2, and TUBG1." (PMID 25830658, 2015). "Moreover, polymorphisms in the AURKA gene are associated with increased risk of primary breast cancer." (PMID 23186136, 2012). "AURKA is associated with worse prognosis in estrogen receptor positive breast carcinomas." (PMID 23186136, 2012). "We have further shown that AURKA amplification is correlated with AURKA overexpression, and AURKA mRNA overexpression has previously been shown to be associated with tumor proliferation, tumorigenesis, clinical aggressiveness, and tumor progression in different cancer types including breast cancer." (PMID 36717329, 2023). "Because we have previously demonstrated the causative role of aberrant AURKA activity in driving the development of breast cancer metastases, we aimed to establish whether NOTCH3 expression was required to mediate AURKA-induced highly invasive capacity of vMCF-7∆Raf1 1GX cells." (PMID 30180881, 2018). "In addition, the AURKA rs1047972 polymorphism, which results in a valine-to-isoleucine substitution, has been investigated for its association with breast cancer, and this polymorphism has been found to be a protective factor for breast cancer in Caucasians but not in Asians." (PMID 28152093, 2017). "Comparing the prognostic value of FGD3 in breast cancer with the prognostic value of genes associated with proliferation such as MKI67, PCNA, and AURKA indicates that FGD3 may offer superior disease progression metrics in all clinically relevant breast cancer subtypes." (PMID 32913979, 2017). "However, the available data on whether high AURKA expression is associated with worse prognosis in breast cancer remain controversial." (PMID 23186136, 2012). "Immunoprecipitation/immunofluorescence results highlighted an interaction of pAURKA with fate-determinant pNUMB; hinting towards the existence of an AURKA/pNUMB axis for mesenchymal fate induction in breast cancer cells." (PMID 42289849, 2026). "Although AURKA amplification has been reported in colorectal and breast cancers, prior work detected CNV in only three of 224 hepatitis B virus-negative HCC cases." (PMID 41515655, 2026). "In a breast cancer study, researchers using kinome‐rewiring techniques discovered that AURKA inhibition reduced the efficacy of PI3K inhibitors." (PMID 40702875, 2025). "In parallel, JAB-2485, another AURKA inhibitor, is under clinical evaluation in patients with solid tumors, including breast cancer (NCT05490472)." (PMID 40949156, 2025). "AURKA inhibitors represent a potentially transformative strategy for overcoming drug resistance in breast cancer." (PMID 40949156, 2025).